TFPI2 (tissue factor pathway inhibitor 2)
Diseases named in the same sentence as TFPI2 in open-access papers (continued):
Sharing a sentence is not in itself a finding about the gene and the disease.
tumor (continued). "On the other hand, pRCC showed upregulation of TFPI2, FSTL1, FAS, and PIGR in the epithelial/tumor, C1QTNF3 and GRN in the endothelial, and ITGAX, HLA-DQA1, IL4I1, and CTSC in the immune compartments." (PMID 38703764, 2024). "Silencing of FTO results in up-regulation of TFPI-2 expression (i.e. through restoring m6A/YTHDF1 mediated stability of TFPI-2 mRNA), and inhibits PC proliferation, invasion in vitro, and tumor growth in vivo." (PMID 39153052, 2024). "The results showed that compared with the oe-NC group, the tumor volume and weight in the oe-CYP24A1 group and the oe-TFPI2 group were significantly reduced." (PMID 39068476, 2024). "The results showed that compared to the oe-NC group, the tumor metastatic nodules in the lungs of the oe-CYP24A1 and oe-TFPI2 groups were significantly reduced." (PMID 39068476, 2024). "Other studies reported that HE4, TFPI2, and epithelial cell adhesion molecule (EpCAM, CD326) are tumor markers, and recent studies have shown that miRNAs in peripheral blood are highly sensitive markers." (PMID 37712874, 2023). "Many TFPI2 downstream signaling pathways are affected upon MBD3 depletion, such as matrix metalloproteinases (MMPs), PI3K and AKT, which are primary factors in tumour growth and metastasis." (PMID 35501390, 2022). "Serum TFPI2 levels were significantly higher in CCC patients (mean ± SD, 508.2 ± 812.0 pg/mL) than in patients with benign lesions (154.7 ± 46.5), BOTs (181 ± 95.5) and other EOCs (265.4 ± 289.1)." (PMID 34009487, 2021). "Regarding the molecular characteristics of TFPI2, the CCC-specific elevation of serum TFPI2 was in accordance with its mRNA expression in both ovarian CCC cell lines and tumor tissues in our previous study." (PMID 34009487, 2021). "Reduced TFPI-2 expression in pancreatic cancer 15 cervical cancer 16 and NPC 17 can consequently promote tumor invasion and metastasis." (PMID 33967612, 2021). "Tanemura at al. demonstrated that during tumor progression, several tumor-related genes and loci, including WIF1, SOCS1, RASSF1A, TFPI2, MINT17, and MINT31, gain methylation with advancing stages." (PMID 34575678, 2021). "Univariate analysis indicated that age, stage, TFPI2, and metastasis, but not tumor thickness, mitotic count or diameter, were significantly associated with overall survival in the UM patients (P = 0.02 for age of diagnosis, 0.008 for stage and metastasis, 0.003 for TFPI2)." (PMID 34249699, 2021). "To validate the results from RNAseq, we measured expression of six genes (COL1A1, FN1, MMP2, TFPI2, CDK6, and CDK4) that were significantly up-regulated in tumor cells compared to normal epithelium by RT-qPCR." (PMID 33142242, 2020). "In vitro models of monocultures and co-cultures were established with tumor cells and fibroblasts to explore the changes of TFPI-2 expression and epigenetic modifications of the TFPI2 gene." (PMID 32559232, 2020). "On the contrary, the combination treatment up‐regulated expression of several known tumour suppressor genes like CST6, TFPI2, GSTP1 and several others." (PMID 32720467, 2020). "Nonetheless, we decided to focus on 4 TSGs (TFPI2, SOX17, GATA4, and FBN2) because we later confirmed that these genes had a cancer-specific methylation pattern in primary OSCC tumor samples." (PMID 31405379, 2019). "There are a further eight tumor-suppressor genes (DLEU2, CDKN2C, SPRY4, UBE2QL1, LIN9, TFPI2, LRIG3, DUSP1) and six genes serve as both oncogenes and tumor-suppressor genes (FOXO1, CAV1, KLF6, CDK6, PLK1, CTGF)." (PMID 30563222, 2018). "In the current study, we compared the methylation level of TFPI2 among the GC and CRC and the adjacent non-tumor tissues, and colorectal normal tissues." (PMID 29137404, 2017). "Secretion of TFPI-2 into the ECM inhibits plasmin-mediated activation of MMPs and maintains the integrity of the ECM, therefore repressing tumor cell invasion." (PMID 29051606, 2017).
tumor (continued). "Far fewer metastatic nodules developed in the TIG group compared to the IG group, demonstrating that TFPI-2 overexpression restrained OC2 metastasis and alleviated tumor malignancy." (PMID 25179542, 2014). "TFPI-2 plays an important role in normal ECM remodeling, and is also becoming increasingly recognized as a tumor suppressor gene." (PMID 22208663, 2012). "In this study, we evaluated the transcriptional levels and methylation status of TFPI-2 in NPC cell lines and analyzed the methylation status of TFPI-2 in a set of NPC primary tumor biopsies." (PMID 21062455, 2010). "To confirm the presence of TFPI-2 and asTFPI-2 transcripts in a normal (HUVEC) and a tumor (Colo-205) cell line, we performed Northern hybridizations using an asTFPI-2 specific cDNA radiolabeled probe." (PMID 17352822, 2007). "As expected, both 5' and 3'-RACE analyses of total RNA from either normal tissue (placenta) or a tumor sample (lung tumor) resulted in a single amplification product containing the 5'-UTR and 3' – poly (A)+ tail regions of wild-type TFPI-2 cDNA." (PMID 17352822, 2007). "By inhibiting plasmin, TFPI-2 effectively decreases activation of MMP-1, MMP-3 and MMP-9, and reduces the invasive potential of several tumour cell lines including A549, an NSCLC cell line." (PMID 15685245, 2005). "Tissue factor pathway inhibitor 2 (TFPI‐2) mRNA is m6A‐modified and stabilized by binding to YTHDF1, which upregulates TFPI‐2 expression and suppresses tumor growth, migration, and invasion, but removal of m6A‐modification by FTO reduces TFPI‐2 expression and promotes cancer progression." (PMID 40448344, 2025). "Among the DEGs, TFPI2 showed the greatest overexpression in the non-recur group (p = 2.09 × 10−6 in the tumor area); indeed, expression of this gene was highest across all three areas in this group." (PMID 40422184, 2025). "Furthermore, LIM homeobox domain 6 (LHX6) suppresses Wnt/β-catenin signaling and upregulates TFPI2 through transcription factors like paired-like homeodomain transcription factor 2 (PITX2), contributing to tumor suppression and reduced cancer cell growth." (PMID 40361374, 2025). "Tissue Factor Pathway Inhibitor 2 (TFPI‐2), a Kunitz‐type serine protease inhibitor, impedes the invasion and metastasis ability of tumour cells via inhibiting the activities of Matrix Metallopeptidase 1 (MMP1), Matrix Metallopeptidase 3 (MMP3), plasmin and trypsin." (PMID 39462685, 2024). "Additionally, CD24 regulates key factors like STAT3 and tissue factor pathway inhibitor-2 (TFPI-2), influencing tumor metastasis by affecting their expression and activity." (PMID 38313430, 2023). "In addition to its cytotoxic activity, Amblyomin-X can regulate cell adhesion and migration of human tumor cells like TFPI and TFPI-2." (PMID 36052162, 2022). "On the contrary, the TFPI-2, originally identified by TFPI-1 homology as placental trypsin and serine protease inhibitor associated with tumour cell ECM, does not physiologically exert any inhibitory activity on the TF pathway." (PMID 36224457, 2022). "Second, the newly reported tumor marker of tissue factor pathway inhibitor 2 (TFPI2) was not assessed." (PMID 36359203, 2022). "Similarly, it has been suggested that LCT13, a tumor-specific long non-coding LCT, induces repression of the 300 kb distant tumor suppressor gene tissue factor pathway inhibitor 2 (TFPI-2) in various malignancies." (PMID 35298627, 2022). "Namely, TFPI is involved in inhibiting the pro-coagulatory activity of TF, but it does not balance the activity of TF, while TFPI-2 seems to be a factor regulating the processes of tumor growth and progression." (PMID 33947134, 2021). "Notably, TFPI2 knockdown decreased the migration of C918 cells along blood vessels, reducing the presence of GFP-positive C918 cells at the periphery of the tumor." (PMID 34249699, 2021).
tumor (continued). "Methylation of several tumor-related genes, including MINT17, MINT31, TFPI2, WIF1, RASSF1A, and SOCS1, comprising the first melanoma CIMP, increased significantly with advanced clinical stages, suggesting that their inactivation is associated with tumor progression." (PMID 34944843, 2021). "It seems that, cancer cell DNA methylation alone is not sufficient to inhibit TFPI-2 as fibroblasts from the cervix are capable to secrete this factor into the tumor stroma." (PMID 32559232, 2020). "TFPI-2 inhibits a wide variety of serine proteinases including plasmin and trypsin, which activate several pro-matrix metalloproteinases (MMPs) and diminish ECM degradation, a process important for tumor invasion and metastasis." (PMID 32132611, 2020). "Since secretion of TFPI2 was also attenuated after TET1 KO, considering TFPI2 was a tumor suppressor of CRC and had been reported inhibited proliferation, we inferred H3R117A inhibited proliferation of LoVo cells by regulating TET1-mediated secretion of TFPI2." (PMID 30651599, 2019). "Next, we selected several EZH2 or LSD1 potential targets (P15, P21, KLF2, PTEN, TFPI2, LATS2, E-cadherin, and RND3) with tumor-suppressive role, and hypothesized that some of which may be associated with AGAP2-AS1-mediated carcinogenicity." (PMID 31186379, 2019). "Four genes (TFPI2, SOX17, GATA4, and FBN2) satisfied the criteria of “cancer-specific methylation” with high-frequency methylation in cell lines, no/undetectable methylation in normal oral mucosa, and frequent methylation in primary OSCC tumor samples." (PMID 31405379, 2019). "TFPI2 is well known as a tumor suppressor gene and inhibits not only the factor VIIa/tissue factor complex but also plasmin, kallikrein, and trypsin." (PMID 29757260, 2018). "The Cancer Genome Atlas (TCGA) database also validated the percentage of methylated reference (PMR) of TFPI2 gene in tumor tissues was higher than that in non-tumor adjacent tissues." (PMID 29137404, 2017). "EYA4, TFPI2 and TLX1 were hypermethylated in more than 90% of all tumours examined." (PMID 28351398, 2017). "Three genes, EYA4, TLX1 and TFPI2 are hypermethylated in >90% of all tumour samples, regardless of CIMP subtype." (PMID 28351398, 2017). "TFPI2 methylation was measured by quantitative methylation-specific polymerase chain reaction (qMSP) method in 114 GC and 80 CRC tissues and their paired non-tumor tissues." (PMID 29137404, 2017). "Tissue factor pathway inhibitor-2 (TFPI-2) is a serine protease inhibitor that exerts multiple physiological and patho-physiological activities involving the modulation of coagulation, angiogenesis, tumor invasion, and apoptosis." (PMID 27349742, 2016). "We evaluated the serum levels of TFPI2 and CA125 in CCC patients according to FIGO tumor stages." (PMID 27798689, 2016). "The controversial role of TFPI1 in tumor progression, together with our finding that only TFPI1α, but neither TFPI1β nor TFPI2, was specifically up-regulated in MCF7 DOXRes cells, prompted us to focus on TFPI1α." (PMID 26501324, 2015). "In humans, TFPI-2 is inactivated or absent during tumor progression, conferring an important role for this gene in the pathogenesis of malignancies." (PMID 24695110, 2014). "TFPI-2 has been recently proposed as TSG since it plays a significant role in the maintenance of the stability of the tumor microenvironment and in the prevention of cancer progression by inhibiting tumor-related angiogenesis and members of ECM." (PMID 24695110, 2014). "Compared with the group with low/high TFPI-2 expression, the TFPI-2 negative group was more likely to have tumor relapse." (PMID 23497249, 2013). "The two remaining patients (patients 2 and 5) expressed low levels of TFPI-2 RNA in the normal tissue with no further decrease in the tumour consistent with the lack of LCT13 expression." (PMID 23703216, 2013).
tumor (continued). "TFPI-2 is a Kunitz-type serine protease inhibitor homologous to tissue factor pathway inhibitor (TFPI), and its down-regulation in cancer has been proposed to contribute to tumour malignancy due its role in ECM remodelling." (PMID 23703216, 2013). "Several studies have provided suggestive evidence that TFPI-2 is inactivated or absent during tumor progression." (PMID 21062455, 2010). "The present work demonstrated that epigenetic inactivation of TFPI-2 by promoter hypermethylation is a frequent and tumor specific event in NPC and TFPI-2 might be considering as a putatitive tumor suppressor gene in NPC." (PMID 21062455, 2010). "To assess whether TFPI-2 might possess properties as a tumor suppressor gene in NPC, we examined the effect of TFPI-2 on clonogenicity, cell proliferation, and cell mobility." (PMID 21062455, 2010). "As matrix degradation is an important step in tumor invasion and metastasis, several, but not all, tumor cells downregulate TFPI-2 expression." (PMID 17352822, 2007). "The quantiscan analysis of each amplicon indicated, on average, that there are ~10 fold more TFPI-2 copies in normal tissue in comparison to tumor tissues, and that TFPI-2 is absent in many tumor cell lines (HepG2, Capan-2 and Colo-205)." (PMID 17352822, 2007). "The existence of a novel TFPI-2 transcript predominantly in tumor cells has not been previously reported." (PMID 17352822, 2007). "Seven primary NSCLC tumour samples and seven nonaffected biopsies obtained from the same patients were examined using this method, and these samples were chosen according to TFPI-2 gene expression (real-time PCR) and methylation status as evaluated by RE-PCR." (PMID 15685245, 2005). "Hypermethylation of the TFPI-2 gene promoter was demonstrated by restriction enzyme-polymerase chain reaction in 12 of 40 cases of NSCLC (30%), including nine of 17 for whom tumour TFPI-2 gene expression was lower than in noncancerous tissue." (PMID 15685245, 2005). "In contrast, for the two others, the TFPI-2 gene promoter was unmethylated in both the tumour and noncancerous tissues." (PMID 15685245, 2005). "Within tumours, both stroma and cancerous cells appeared to synthesise varying amounts of TFPI-2 protein, and the staining score was well correlated with the number of TFPI-2 mRNA copies measured by real-time PCR (r=0.65, P<0.01)." (PMID 15685245, 2005). "Such a difference in TFPI-2 gene expression between the tumour and the corresponding noncancerous lung was found in 34 patients." (PMID 15685245, 2005). "In four patients TFPI-2 gene expression was decreased within the tumour compared to nonaffected tissue, and in two of them 26 of 28 CpG dinucleotides were methylated." (PMID 15685245, 2005). "Highly variable amounts of TFPI-2 mRNA were measured within both the nonaffected lung (32–20 400 copies/107 18S RNA) and the tumour (15–336 000 copies) and the distribution of values obtained was similar in both categories of tissue (P=0.5)." (PMID 15685245, 2005). "In contrast, this epigenetic modification was shown in only three of 23 tumours in which no decrease in TFPI-2 synthesis was found (P=0.016)." (PMID 15685245, 2005). "We also found that the TFPI-2 gene promoter sequence was hypermethylated in three of 23 cases of NSCLC although mRNA levels within the tumours were not decreased." (PMID 15685245, 2005). "In vivo, TFPI2 overexpression significantly reduced tumor volume and size in sorafenib-treated mice, consistent with a higher proportion of PARP-positive and TUNEL-positive cells and lower Ki67 expression, indicating enhanced sorafenib-induced apoptosis in TFPI2-overexpressing cells." (PMID 40765823, 2025). "TFPI2 expression was absent in non-tumor endometrial and myometrial tissues." (PMID 40361374, 2025).
tumor (continued). "Furthermore, FTO inhibited the expression of TFPI-2 mRNA through the m6A reader YTHDF1, leading to the down-regulation of TFPI-2 expression and ultimately promoting the proliferation, colony formation, sphere formation, migration, and invasion of PAAD cells, as well as tumor growth in vivo." (PMID 37916161, 2023). "However, unlike other Kunitz-type inhibitors, such as TFPI and TFPI-2, Amblyomin-X showed tumor cell specificity." (PMID 36052162, 2022). "Although the methylation of TFPI2 in OSCC has been identified using a genome-wide methylation array, its promoter hypermethylation associated with transcriptional silencing was not validated in OSCC tumor samples." (PMID 31405379, 2019). "Among these genes, TFPI2, SOX17, and GATA4 were frequently hypermethylated in both OSCC and oral cancer patient samples in a cancer-specific manner, suggesting that these genes may play a role as tumor suppressors in OSCC." (PMID 31405379, 2019). "The present study identifies the proteolytic cleavage of extracellular TFPI-2 by trypsinogen 4 as a new pathway regulating the response of tumor endothelial cell to the factors VEGF-A,FGF-2 and EGF (which characterize the angiogenic milieu), and hence tumor angiogenesis." (PMID 26318044, 2015). "TFPI-2 protein expression was present in the tumor, peritumoral and gastric normal tissues, but TFPI-2 protein expression was stronger in gastric normal tissue than in peritumoral tissue and tumor tissue, and stronger in peritumoral tissue than in gastric normal tissue." (PMID 24396436, 2014). "However, there was a statistically significant difference in the level of TFPI-2 protein expression between the patients with and without tumor invasion or metastasis (P<0.05)." (PMID 24396436, 2014). "However, there was a statistically significant difference in the level of TFPI-2 mRNA expression between the patients with and without tumor invasion or metastasis (P<0.05)." (PMID 24396436, 2014). "In addition, TFPI-2 can inhibit vascular endothelial growth factor that is involved in promoting tumor angiogenesis by a negative feedback mechanism." (PMID 23497249, 2013). "Four samples (i.e. two from the nonaffected lung and two from the tumour) were analysed for 25 patients, and the number of TFPI-2 mRNA copies measured within two biopsies obtained from the same tissue never varied more than four-fold (mean=1.8, and range=1.1–3.9)." (PMID 15685245, 2005). "However, in one case, a high rate of promoter methylation was identified, although TFPI-2 mRNA levels were comparable in nonaffected lung tissue and the tumour." (PMID 15685245, 2005). "However, differences in TFPI-2 mRNA levels were recorded when we analysed two biopsies sampled within the same tissue (either nonaffected lung or tumour), although they were never more than four-fold." (PMID 15685245, 2005). "Cox’s regression analysis indicated that TFPI-2 expression, histologic grade, and vessel invasion might be significant prognostic factors for DFS, while TFPI-2 expression and histologic grade were the most significant independent predictors for tumor recurrence." (PMID 23497249, 2013). "In contrast, the band intensities of PCR products were similarly reduced after RE-PCR on tumour and noncancerous tissue DNA in 28 patients compared to the intensity of undigested DNA (see Pat 2), and this result supported the unmethylated status of TFPI-2 gene promoter in these cases." (PMID 15685245, 2005). "In clinical settings, CA125 is a non-specific, but sensitive serum tumor marker to detect EOC and TFPI2 will be simultaneously evaluated to predict CCC preoperatively." (PMID 34009487, 2021). "We also showed a high frequency (88.6%) of TFPI-2 promoter hypermethylation in NPC primary tumor biopsies but not in the NNE tissues, which implied that transcriptional silencing of the TFPI-2 pathway might be involved in NPC tumorigenesis." (PMID 21062455, 2010).
tumor (continued). "Significantly, although the methylation of TFPI2 in OSCC has been detected through a comprehensive methylation array analysis, the connection between TFPI2 promoter hypermethylation and the consequent suppression of gene transcription in OSCC tumor samples has not been confirmed through validation." (PMID 38067304, 2023).